COPS4 (COP9 signalosome subunit 4)
Description:
Component of the COP9 signalosome complex (CSN), a complex involved in various cellular and developmental processes. The CSN complex is an essential regulator of the ubiquitin (Ubl) conjugation pathway by mediating the deneddylation of the cullin subunits of SCF-type E3 ligase complexes, leading to decrease the Ubl ligase activity of SCF-type complexes such as SCF, CSA or DDB2. Also involved in the deneddylation of non-cullin subunits such as STON2.
Synonyms: SGN4; CSN4
Tractability: PROTAC: ubiquitination databases record sites on it; its protein half-life has been measured.
Gene: Protein-coding gene on chromosome 4 (83,034,447 to 83,075,818, forward strand). Ensembl gene ENSG00000138663.
Subcellular location: Cytoplasm; Nucleus; Cytoplasmic vesicle, secretory vesicle, synaptic vesicle
Subcellular location (Human Protein Atlas): Nuclear speckles
Pathways (Reactome):
DNA Repair: DNA Damage Recognition in GG-NER; Formation of TC-NER Pre-Incision Complex
Metabolism of proteins: Neddylation
Signal Transduction: RHOBTB1 GTPase cycle
Vesicle-mediated transport: Cargo recognition for clathrin-mediated endocytosis
Gene Ontology:
Molecular function: protein binding; deNEDDylase activity
Biological process: protein deneddylation; protein neddylation; regulation of protein neddylation
Cellular component: COP9 signalosome; cytoplasm; nuclear speck; nucleus; synaptic vesicle; cytosol; nucleoplasm; protein-containing complex
Genetic constraint (gnomAD): Loss-of-function variants: 5 observed, 34.56 expected, observed/expected ratio (o/e) 0.14, 90% interval 0.075 to 0.3. The upper end of that interval is the gene's LOEUF score, 0.3, which puts it in group 1 of 6, group 1 being the genes least tolerant of losing a copy. Missense variants: 174 observed, 337.12 expected, observed/expected ratio (o/e) 0.52, 90% interval 0.46 to 0.58. Synonymous variants: 127 observed, 121.34 expected, observed/expected ratio (o/e) 1.05, 90% interval 0.9 to 1.21.
Homologues: Orthologues: chimpanzee COPS4 (100% identical), pig COPS4 (100% identical), mouse Cops4 (99% identical), rat Cops4 (99% identical), rabbit COPS4 (95% identical), zebrafish cops4 (95% identical), tropical clawed frog cops4 (92% identical), guinea pig COPS4 (91% identical), macaque COPS4 (90% identical), Drosophila melanogaster CSN4 (71% identical), Caenorhabditis elegans csn-4 (36% identical). Paralogues in human: PSMD12 (21% identical).
Diseases named in the same sentence as COPS4 in open-access papers:
COPS4 is named in the same sentence as 8 diseases in open-access papers, as found by Europe PMC text mining. Sharing a sentence is not in itself a finding about the gene and the disease. The quoted sentences say what the papers report.
breast carcinoma (1 paper, 2021). "Of interest for future study are top sensitivity hit UGP2 and resistance hit COPS4 which were the most lowly expressed and highly expressed screen hits in the large chemotherapy treatment‐resistant breast cancer patient tumor cohort." (PMID 33932086, 2021).
melanoma (1 paper, 2018). A malignant, usually aggressive tumor composed of atypical, neoplastic melanocytes. "CTAG1B, BRCA2, and SPAG8 have been previously shown to induce humoral immune response in BC and other cancer patients, ANKRD30BL and COPS4 were previously found to elicit autoantibody response in gastric and thyroid cancer and melanoma." (PMID 30515157, 2018). "We have previously found anti-COPS4 IgG in gastric and thyroid cancer and melanoma, however the reasons for its immunogenicity are not clear." (PMID 30515157, 2018).
cancer (3 papers, 2018 to 2022). A tumor composed of atypical neoplastic, often pleomorphic cells that invade other tissues. "A study using CRISPR to systematically perturb 222,784 gene pairs in two cancer cells lines determined a genetic interaction between SMC5 and a CSN component, COPS4, which resulted in a growth abnormality." (PMID 32384871, 2020).
COPS4 also shares sentences with these, for which no sentence is quoted: infection (1 paper); neuroblastoma (1); prostate carcinoma (1); thyroid cancer (1); tumor (1).